MLNR (motilin receptor)
Description:
Receptor for motilin.
Synonyms: GPR38; MTLR1
Tractability: Small molecule: a drug acting on it is in phase 2 or 3 trials; a structure with a bound ligand is known; a high-quality ligand is known; it belongs to a druggable protein family. Antibody: its Gene Ontology location is reachable by antibodies, with high confidence; UniProt places it where antibodies can reach, with medium confidence; UniProt predicts a signal peptide or a membrane-spanning region. PROTAC: a small molecule that binds it is known. Other modalities: a drug acting on it is in phase 2 or 3 trials.
Target class: Short peptide receptor (family A GPCR); Family A G protein-coupled receptor; Peptide receptor (family A GPCR); Membrane receptor; Motilin receptor
Gene: Protein-coding gene on chromosome 13 (49,220,118 to 49,225,201, forward strand). Ensembl gene ENSG00000102539.
Subcellular location: Cell membrane
Subcellular location (Human Protein Atlas): Cytosol; Plasma membrane
Pathways (Reactome):
Signal Transduction: G alpha (q) signalling events; Peptide ligand-binding receptors
Gene Ontology:
Molecular function: G protein-coupled peptide receptor activity; hormone binding; protein binding; G protein-coupled receptor activity
Biological process: G protein-coupled receptor signaling pathway; cell communication; signaling
Cellular component: plasma membrane; membrane
Genetic constraint (gnomAD): Loss-of-function variants: 16 observed, 16.35 expected, observed/expected ratio (o/e) 0.98, 90% interval 0.66 to 1.48. The synonymous counts are far from expectation, so gnomAD's model fits this gene poorly and the ratio says little. Missense variants: 630 observed, 527.74 expected, observed/expected ratio (o/e) 1.19, 90% interval 1.12 to 1.27. Synonymous variants: 302 observed, 245.62 expected, observed/expected ratio (o/e) 1.23, 90% interval 1.12 to 1.35.
Homologues: Orthologues: chimpanzee MLNR (99% identical), macaque MLNR (93% identical), rabbit MLNR (84% identical), pig MLNR (84% identical), dog MLNR (75% identical), zebrafish mlnr (37% identical), tropical clawed frog mlnr (23% identical). Paralogues in human: GHSR (44% identical), NTSR1 (31% identical), NMUR1 (27% identical), NTSR2 (25% identical), NMUR2 (25% identical), GPR39 (24% identical), TRHR (22% identical), NMBR (18% identical), EDNRB (18% identical), GRPR (18% identical), EDNRA (17% identical), BRS3 (17% identical), and 3 more.
Diseases named in the same sentence as MLNR in open-access papers:
MLNR is named in the same sentence as 12 diseases in open-access papers, as found by Europe PMC text mining. Sharing a sentence is not in itself a finding about the gene and the disease. The quoted sentences say what the papers report.
gastroparesis (5 papers, 2017 to 2025). Paralysis of the muscles of the stomach wall resulting in delayed emptying of the gastric contents into the small intestine. "They emphasize the effectiveness of prokinetic drugs like itopride, metoclopramide, and motilin receptor agonists, such as erythromycin, in treating gastroparesis." (PMID 39314225, 2024). "Clinical interest in motilin includes the long standing use of erythromycin, an antibiotic with motilin receptor (MLNR) agonist activity, to treat intestinal dysmotility conditions such as gastroparesis." (PMID 38544692, 2024). "Erythromycin, primarily invented as an antibiotic medicament, showed agonistic effects on the motilin receptor and therefore has a beneficial effect on resolving gastroparesis." (PMID 36902534, 2023). "In the upper gut, this peptide is the most important factor in controlling the interdigestive migrating motor complex (MMC), and motilin receptor agonists have been proposed for treating gastroparesis or conditions with slow gastric emptying." (PMID 29082242, 2017).
breast carcinoma (1 paper, 2019). "In conclusion, our results demonstrated that mLNR is an independent prognostic factor in breast cancer patients and the G-R staging system could be an indication model for DSS among patients with different molecular subtypes." (PMID 31305469, 2019).
depression (1 paper, 2021). "It is also of note that macrolide antibiotics, which act as motilin receptor agonists, have been associated with the emergence of manic symptoms, including a report of a “switch” to mania in a patient with depression." (PMID 34575041, 2021). "Finally, when considering the therapeutic potential of drugs acting via motilin receptors in patients with depression, certain clues may be obtained from clinical trials of drugs acting on the motilin receptor in other conditions." (PMID 34575041, 2021). "While these findings cannot be generalized directly to patients with depression, it may be possible that motilin receptor agonists have distinct actions in depressed and non-depressed individuals." (PMID 34575041, 2021).
Obesity (1 paper, 2023). Accumulation of substantial excess body fat. "The intravenous infusion of motilin or the motilin receptor agonist erythromycin induces antral contractions and hunger sensations in lean volunteers and volunteers with obesity." (PMID 37836548, 2023).
prostate tumor (1 paper, 2013). "ARLTS1 and MLNR had a correlation value of −0.35 (p-value 0.04) in PCa cell lines, and ARLTS1 and SPRYD7 had a correlation value of −0.34 (p-value 0.003) in prostate tumour specimens." (PMID 23940804, 2013).
type 1 diabetes (1 paper, 2019). "Some work has been done on piperidinamine-containing molecules as motilin-receptor agonists and their clinical development for treating type 1 diabetes." (PMID 30650074, 2019).
cancer (3 papers, 2019 to 2020). A tumor composed of atypical neoplastic, often pleomorphic cells that invade other tissues. "mLNR has been known as an independent prognostic factor in various malignant tumors, including the stomach, pancreas, breast, thyroid gland, cervix, and salivary glands." (PMID 31683773, 2019). "NTSR1, NTSR2, GHSR, MLNR, and NMUR1 promoter hypermethylation presented discriminative ROC curve profiles, which clearly differentiate cancer tissues from normal tissues [Area Under Curve (AUC) = 0.6220, 0.5736, 0.8103, 0.6049, and 0.5631, respectively]." (PMID 31974445, 2020). "Moreover, MLNR, IGHE and RPL10L are only obtained by MVSPL, these genes are targets for cancer drugs." (PMID 31534156, 2019).
MLNR also shares sentences with these, for which no sentence is quoted: Anxiety (1 paper); Autoimmunity (1); COVID-19 (1); multiple sclerosis (1); tumor (1).